STAT3 (signal transducer and activator of transcription 3)
Diseases named in the same sentence as STAT3 in open-access papers (continued):
Sharing a sentence is not in itself a finding about the gene and the disease.
glioma (continued). "Given that, STAT3 expression was depleted by transfection with small interfering RNA (siRNA) in glioma cells, in an attempt to elaborate whether STAT3 has a certain bearing on FOXP1 in glioma cells." (PMID 30134017, 2018). "Interestingly, tetraspanin CD9, normally enriched in exosome membranes, has recently been reported to stabilize gp130, thereby facilitating activation of STAT3 signaling in glioma stem cells." (PMID 29867925, 2018). "Other molecular pathways that have been described to promote radiation-induced invasion in glioma include melanoma differentiation-associated gene 9 (MDA-9), the transcription factor signal transducer and activator of transcription 3 (STAT3), and the chemokine receptor CXCR4." (PMID 30463322, 2018). "The mRNA and protein expression levels of STAT3 were highly expressed in glioma tissues and cells." (PMID 30134017, 2018). "Depleted STAT3 restrained cell proliferation and invasion, promoted cell apoptosis in glioma cells." (PMID 30134017, 2018). "STAT3 knockdown also attenuated increased invasion of glioma cells induced by radiation." (PMID 29571296, 2018). "The results of a previous study confirmed that STAT3 promoted glioma progression." (PMID 29132362, 2017). "Based on these knowledge,we speculated that SH3GL2 might negatively regulate STAT3 which would affect the expression of MMP2 in human glioma cells." (PMID 28470949, 2017). "Our results showed that the growth of U251 cells was inhibited by CTS in a dose-dependent manner, which was partly reversed by STAT3C overexpression, indicating that the inhibitory effect of CTS on glioma cell proliferation is dependent on the suppression of STAT3 activation." (PMID 28492557, 2017). "Taken together, these results illustrate that SH3GL2 may play an important role in inhibiting glioma cell migration and invasion by suppressing STAT3/MMP2 signalling pathway." (PMID 28470949, 2017). "The STAT3 pathway has a universal radioresistance-promoting function in many cancer types, including non-small cell lung cancer, squamous cell carcinoma, and head and neck carcinoma, as well as glioma." (PMID 29246031, 2017). "Taken together, our data suggest that TRIM24 is a co-activator of STAT3 in gliomas." (PMID 29129908, 2017). "Furthermore, STAT3 was shown to be essential in human glioma cells to maintain their tumor initiating capacity and the ability to invade the normal brain." (PMID 28030813, 2017). "Because of the well-established role of STAT3 in cancer stem cells and embryonic stem cells, we decided to examine whether our newly discovered spDSBs play any roles in glioma stem cells." (PMID 28337983, 2017). "It has been suggested that controlling pro-survival signaling pathways as well as other molecular targets like STAT3 may represent a novel and effective therapeutic strategy for the treatment of gliomas." (PMID 28877265, 2017). "We found that STAT3 inhibitor increased the sensitivity of glioma cells to chemotherapeutic drugs." (PMID 29284440, 2017). "Furthermore, miR-6743-5p plays an essential role in the proliferation and apoptosis of glioma cells through modulating GRIM-19/STAT3." (PMID 29074558, 2017). "Only one prior study investigated STAT3 after metformin treatment in glioblastoma and observed a reduced phosphorylation at the Y705 binding site, but the results were merely based on two established glioma cell lines." (PMID 28030813, 2017). "Taken together, our data demonstrate that TRIM24 recruits STAT3 to chromatin in EGFR-driven glioma cells, which is dependent on H3K23ac association, thus providing evidence that TRIM24 binds with EGFR-upregulated H3K23ac, and then recruits STAT3 and stabilizes its interaction with chromatin." (PMID 29129908, 2017). "Many brain cancers show characteristic metabolic shifts towards aerobic glycolysis and extensive utilization of TCA cycle intermediates, and the constitutionally active STAT3 may play such modulatory roles in glioma metabolism." (PMID 28346397, 2017).
glioma (continued). "Likewise, in glioma spheres, Notch inhibition significantly decreased Akt and STAT3 phosphorylation and reduced survival of glioma CSCs." (PMID 26713603, 2016). "It remains unclear whether there is cross-talk between the AKT and STAT3 signaling pathways or they work independently to promote progression of glioma." (PMID 27893430, 2016). "Having found that IL-10 secreted from M2 macrophages was dependent on the JAK2/STAT3 signaling pathway and that co-culture with glioma cells was able to activate the JAK2/STAT3 signaling pathway in M2 macrophages, we've next tried to understand how IL-10 was dependent on JAK2/STAT3 pathway." (PMID 27765933, 2016). "Moreover, HMGA2 expression is positively correlated with expressions of STAT3 and C/EBPβ, two essential transcription factors that promote mesenchymal phenotypes in GBMs; as well as that of CD44, another hallmark of glioma invasiveness." (PMID 27259253, 2016). "Furthermore, we for the first time found that IL-10 stimulated the JAK2/STAT3 pathway in glioma cell lines U271 and U87 through interaction with JAK2 in a protein-protein interaction fashions." (PMID 27765933, 2016). "Phosphorylation of serine 727 is important for STAT3-mediated resistance to ionizing radiation in glioma and, thus, disrupting phosphorylation at this site could provide a potential target for radiosensitization." (PMID 27043632, 2016). "STAT3 has been shown to be constitutively activated in gliomas and medulloblastomas." (PMID 27043632, 2016). "In a separate set of experiments, murine glioma cell lines (Tu-2449, Tu-9648, and Tu-251) with constitutively expressed STAT3 treated with curcumin showed a dose-dependent decrease in the activity of phosphorylated JAK1 and JAK2 and led to downstream inactivation of STAT3." (PMID 27807473, 2016). "STAT-3 has been assumed to modulate the transition from an epithelial to a migratory mesenchymal phenotype in glioblastoma and to promote tumorigenicity of glioma stem-like cells." (PMID 26485029, 2015). "Interestingly, it is becoming apparent that STAT3 is an important molecular player that allows glioma cells to promote the activity of microglia; reciprocally microglia facilitate tumor survival, growth and the spread of glioma cells." (PMID 26157361, 2015). "The uncovering of STAT3 as a target of SR141716 activity, which we believe is novel in cancer, constitutes the molecular bases of this dual activity enclosed in SR141716 molecule and highlight CB1-STAT3 as a potential new oncogenic axis in the complex glioma biology." (PMID 26008966, 2015). "Using GSEA we found that silencing of RTVP-1 induced downregulation of genes that are targets of the TFs STAT3 and C/EBPβ, which further supports our data that RTVP-1 is a downstream mediator of STAT3 and C/EBPβ effects on the mesenchymal transformation of glioma cells." (PMID 26267319, 2015). "Modulation of STAT-3 by ibuprofen or diclofenac may therefore constitute a mechanism of action that could improve the treatment of high-grade glioma." (PMID 26485029, 2015). "The STAT3 pathway may modulate the number of NSCLC- and mesothelioma- ALDHbright cells and, notably, glioma cells of the mesenchymal subtype, which require STAT3 (and CEBPβ) for their survival, exhibited high levels of ALDH1A3 expression." (PMID 25868979, 2015). "Consistent with our findings, STAT3 is among the most frequently activated oncogenic proteins in multiple solid tumor types, and is a predictor of poor prognosis in many malignancies including gliomas." (PMID 25955030, 2015). "The inhibition of STAT3 function in tumor microglia may thus potentially be used as an immunotherapy approach for gliomas." (PMID 26157361, 2015). "We next examined whether RTVP-1 is regulated by C/EBPβ and STAT3, the two transcription factors that were recently reported as master regulators of the mesenchymal transformation of glioma." (PMID 26267319, 2015).
glioma (continued). "Thus we investigated the possible effects of SR141716 on modulating GSK-3β and STAT3 activity in our experimental model starting from U251 glioma cell lines, while confirming it in high- and low-CB1-expressing primary cells." (PMID 26008966, 2015). "So, saw palmetto extract may be useful as an adjunctive therapeutic agent for treatment of individuals with glioma and other types of cancer in which STAT3 signaling is activated." (PMID 26788112, 2015). "Saw palmetto extract may be useful as an adjunctive therapeutic agent for treatment of individuals with glioma and other types of cancer in which STAT3 signaling is activated." (PMID 26788112, 2015). "STAT3 inhibitors have been shown to decrease GBM invasion in human glioma cell line U251." (PMID 24518612, 2014). "Here, we demonstrate that Inositol Polyphosphate-5-Phosphatase F (INPP5F), one of the polyphosphoinositide phosphatases, is differentially expressed in GSCs from glioma patients, and is identified as an inhibitor of STAT3 signaling via interaction with STAT3 and inhibition of its phosphorylation." (PMID 25476455, 2014). "Others have targeted the JAK2/STAT3 pathway in glioma stem-like cells (GSCs)." (PMID 24518612, 2014). "Stat3 is constitutively activated in a subset of malignant gliomas and the expression of constitutively active Stat3 (together with C/EBPβ) has been shown to transform gliomas to a more aggressive mesenchymal subtype." (PMID 25054228, 2014). "Stat3 is a transcription factor central to cancer progression including in gliomas." (PMID 25054228, 2014). "In contrast, expression of the miR-21 gene is suppressed by STAT3 in glioma cells." (PMID 24497923, 2014). "IL-1 also activated Stat3, a transcription factor crucial in glioma progression." (PMID 25054228, 2014). "However, relatively recent evidence suggests that exposure to glioma-derived chemokines induce constitutive STAT3 activation in MG, with consequent suppression of antitumor mechanisms or even tolerance to tumor antigens." (PMID 24518612, 2014). "In addition, IFNB1 in vitro treatment reduced levels of miR-21, one of the most commonly upregulated miRNAs in glioma, via STAT3 activation." (PMID 23468990, 2013). "In combination, these results thus suggest that the STAT3-mediated reduction in IFN signaling may be the mechanism behind the observed STAT3-mediated increase in oHSV replication in glioma cells." (PMID 23936533, 2013). "This may imply that basal levels of STAT3 in glioma cells are sufficient to maintain replication of oHSV and that replication needs endogenous STAT3, since reduction can greatly affect the titers of the oHSV." (PMID 23936533, 2013). "Besides, others have also indicated that control of miR-21 expression at the transcriptional level is regulated by STAT3 in human glioma cells as well as in myeloma and prostate cancer cells." (PMID 23469214, 2013). "Recent studies report that STAT3 signaling is a master regulator of mesenchymal transformation of gliomas and that STAT3 modulated genes are highly expressed in the mesenchymal transcriptome of gliomas." (PMID 23936533, 2013). "Moreover, several studies have demonstrated that inhibition of STAT3 activity reduces glioma growth." (PMID 24244348, 2013). "Here, we hypothesized that alterations in STAT3 signaling in glioma cells may affect the replicative ability of rQNestin34.5." (PMID 23936533, 2013). "Interestingly, we also found that VPA, an HDAC inhibitor, previously shown by us and others to enhance oHSV replication, also increased STAT3 activation in glioma cell and STAT3 reported gene activity." (PMID 23936533, 2013). "In addition, evidence for STAT3 leading to the immunosuppressive milieu of the glioma microenvironment has been mounting." (PMID 23936533, 2013). "Moreover, silencing of STAT3 in a murine glioma model resulted in microglia/macrophages activation and tumor growth inhibition." (PMID 23864876, 2013).
glioma (continued). "Based on this, we hypothesized that STAT3 activation in MG may actually enhance replication of oHSV in glioma cells through its ability to modulate and down-regulate interferon responses." (PMID 23936533, 2013). "Additionally, STAT3 maintains the “stemness” of glioma cells, the mesenchymal transformation of brain tumors and tumor-mediated immune suppression." (PMID 23013619, 2012). "Moreover, we have recently demonstrated that hypoxia can induce the expression of p-STAT3 in glioma cells." (PMID 23013619, 2012). "Likewise, in murine xenograft models of glioblastoma, the mean percentage of p-STAT3-expressing cells in the gliomas resistant to antiangiogenic therapy was markedly elevated relative to controls." (PMID 23013619, 2012). "In the control-treated NSC11 gliomas, the mean percentage of p-STAT3 expressing tumor cells was 9.0 + 4.4% (median 6.4; range: 5.1 – 14.0; n=5), whereas in the bevacizumab-treated cohort, the mean was 24.6 + 6.4% (median 22.7; range: 16.0 – 33.3; n=6; P=0.008 by pair comparison)." (PMID 23013619, 2012). "Furthermore, treatment of human U343 glioma cells with compound HAK-2 led to a clear reduction of p65-mediated STAT3 co-immunoprecipitation." (PMID 21801384, 2011). "We previously reported that IL-1β induces activation of STAT3 in C6 glioma cells." (PMID 21682888, 2011). "The decrease in STAT3 activation by Ad-bFGF-siRNA can induce multiple effects in glioma cells U251." (PMID 21906308, 2011). "Previous reports have indicated key roles for HIF1A and STAT3 in glioblastoma aggressiveness, confirming the validity of this rank-order approach for identifying upstream transcription factors regulating the invasive phenotype of human gliomas." (PMID 20565806, 2010). "Given the fact that STAT3 plays a key role in the mesenchymal transformation of gliomas, which accompanies aggressive behavior, STAT3 may also be a prime target to prevent malignant transformation of low-grade gliomas." (PMID 20840775, 2010). "Because STAT3 has been implicated in malignant transformation and tumor cell survival, and in interacting with Src-dependent signaling, we examined whether STAT3 knockdown would enhance the effects of Src inhibition in glioma cell lines." (PMID 20808823, 2010). "In gliomas, there are several reports on a constitutive activation of STAT3." (PMID 20840775, 2010). "As Iridals interacts with PKCα and RasGRP3-molecules that regulate Akt and STAT3 signaling, and since inhibition of Akt/mTOR and STAT3 signaling are being targeted for GBM treatment we evaluated the effect of Iripallidal on glioma cell proliferation and these signaling pathways." (PMID 20576128, 2010). "Src and STAT3 was over-activated in U87 glioma cells as compared to primary astrocytes." (PMID 20808823, 2010). "Finally, STAT3 was most recently considered to be a master regulator of human gliomas and essential for maintaining tumor initiating capacity and ability to invade the normal brain." (PMID 20840775, 2010). "Therefore, we measured p-STAT-3 in glioma patients' peripheral blood mononuclear cells (PBMCs) and compared these levels to those of healthy donors." (PMID 19900287, 2009). "Signal transducer and activator of transcription-3 (Stat3) was studied along with several steps of the PI3/Akt pathway in a series of 64 gliomas that included both malignant and low-grade tumors, using quantitative immunohistochemistry, Western blotting, and molecular biology techniques." (PMID 19421400, 2008). "In this study, we explored Q-3-Dec as a multi-target agent, which concomitantly impairs NF-κB/STAT3-dependent survival signaling, mitochondrial function, and O6-Methylguanine-DNA Methyltransferase (MGMT) expression, a DNA repair enzyme closely associated with chemoresistance, in glioma cells." (PMID 41751862, 2026). "Thus, convallatoxin suppresses gliomas by regulating the JAK/STAT3 signaling pathway." (PMID 40321161, 2025). "In addition to glioma, STAT3 is hyperactivated in various other types of human cancers." (PMID 40427146, 2025).
glioma (continued). "Furthermore, STAT3 has been found to control the stemness of glioma cells." (PMID 40427146, 2025). "NIBAN2 may promote glioma growth by activating the JAK2/STAT3 signaling pathway." (PMID 40944417, 2025). "Through this technique, we were able to demonstrate that loading STAT3-siRNA onto NLP-EXOSOME COMPLEX resulted in the inhibition of glioma cell growth without causing any toxicity, as well as reduced tumor growth in vivo and improved outcomes for glioma-bearing mice." (PMID 40427146, 2025). "Our detailed analysis, utilizing systematic approaches, established that both the expression of STAT3 and the STAT3 signaling activities are strongly associated with higher WHO grades of glioma, the presence of 1p/19q chromosome 1p/19q non-codeletions, and IDH wild-type status." (PMID 40265014, 2025). "Glioma-associated microglia and bone-marrow-derived macrophages account for up to 40% of tumour cellularity and display a transcriptional convergence on colony-stimulating-factor-1 receptor (CSF1R)– and PI3Kγ-dependent pathways that promote STAT3 activation, efferocytosis and matrix remodelling." (PMID 40995359, 2025). "A comprehensive survival analysis using the TCGA database revealed that glioma patients with elevated STAT3 expression had reduced overall survival, progress free interval, and disease specific survival compared to those with expressed lower levels of STAT3 (p < 0.001)." (PMID 40265014, 2025). "Our approach involved utilizing a unique method of utilizing siRNA packaged in NLP-EXOSOME COMPLEX/STAT3-silencer and evaluating its impact on cultured glioma cells, as well as in a syngeneic tumor transplantation model in mice, which closely mimics human gliomas." (PMID 40427146, 2025). "Additionally, studies have shown that 6’s anti-GBM effect may be due to inactivating the PKCδ/STAT3 signaling pathways, triggering cytotoxic autophagy in glioma cells by suppressing PI3K/AKT/mTOR and enhancing TMZ’s pro-apoptotic effect via NF-κB modulation." (PMID 40076568, 2025). "By inhibiting the JAK/STAT3 pathway, convallatoxin could be a promising treatment for gliomas." (PMID 40321161, 2025). "However, it remains unclear whether Calanquinone A inhibits STAT3 or p65 activation in glioma cells." (PMID 40759869, 2025). "Glioma cells were reported to have the ability to evade the immune system and foster an immunosuppressive milieu by various mechanisms, notably by diminishing the recruitment of immune cells, secreting immunosuppressive cytokines, and activating the STAT3 pathway." (PMID 38903494, 2024). "Presented results indicate that deletion of STAT3 has a significantly suppressive effect on expresison of examined glioma and hypoxia related markers in vitro which could be recapitulated in vivo where, however, this effect is not universal as seen in case of HIF1a and VEGFC expressions." (PMID 38654280, 2024). "Besides, our clinical investigation indicates a negative association between miR-410 expression and STAT3 within the glioma tissues of humans." (PMID 38238515, 2024). "In addition to increased upstream activator activity, any loss-of-function mutation or decreased upstream repressor activity may explain the structural activation of STAT3 in gliomas." (PMID 36923251, 2023). "Similarly, high STAT3 expression promotes glioma cell survival and angiogenesis in brain lower-grade glioma (LGG), which could be another important factor that affects prognosis." (PMID 36977736, 2023). "In addition to siRNA, this vector could provide a pathway for other drugs targeting STAT3 to penetrate the BBB for the treatment of gliomas." (PMID 36923251, 2023). "In addition, IL-6 promoted tumor angiogenesis and tumor growth by activating STAT3 in glioma." (PMID 38259287, 2023). "Furthermore, TMSB10 may involve glioma immune regulation progression by promoting PD-L1 expression levels via activating STAT3 signaling pathway." (PMID 37275863, 2023). "Therefore, we focused our study on the effect of STAT3 on gliomas." (PMID 37724127, 2023).